NUTM1 (NUT midline carcinoma family member 1)
Diseases named in the same sentence as NUTM1 in open-access papers (continued):
Sharing a sentence is not in itself a finding about the gene and the disease.
sarcoma (22 papers, 2016 to 2025). A usually aggressive malignant neoplasm of the soft tissue or bone. "In this paper, the intracranial tumor CIC is mainly fused with NUTM1, which is considered to be a molecular variant of CIC sarcoma." (PMID 40255429, 2025). "NUTM1-rearranged sarcomas have been reported with pathological features in a variety of different soft tissue sites in the body, including the stomach, kidneys, brain, ovaries and gastrointestinal tract." (PMID 41001035, 2025). "Rare cases of CIC::NUTM1 sarcoma in pediatric patients have recently been reported in brain, kidney, bone, and soft tissues." (PMID 38851744, 2024). "NUTM1-rearranged tumors such as skin adnexal poroid neoplasms and CIC::NUTM1 sarcoma are positive for NUT antibody by immunohistochemistry, but these tumors are almost never sinonasal." (PMID 38491228, 2024). "In summary, our patient’s tumor is the first “MPNST” to show an NSD3::NUTM1 fusion, expanding the phenotypic profile of NUT fusion sarcomas." (PMID 39200173, 2024). "NSD3::NUTM1 fusions in sarcomas and their poorly understood biological implications necessitate a deeper examination of their oncogenic activity and clinical significance." (PMID 39200173, 2024). "Small round blue cell tumors with NUTM1 rearrangement (i.e., NUTM1-rearranged sarcomas) have also been described." (PMID 38067300, 2023). "Whereas CIC::LEUTX and CIC::NUTM1 have also been reported in a subset of CIC-rearranged sarcomas, fusions implicating the ATXN1 gene seem to be only encountered in CNS tumors." (PMID 36737790, 2023). "The incidence and clinical course of NUTM1-rearranged sarcomas are presently unclear due to the small number of described cases." (PMID 34898574, 2021). "Recently, NUTM1-rearrangement has been identified in two other major types of neoplasms: hematologic malignancies and sarcomas." (PMID 34898574, 2021). "In this study, we report the clinical, lung cancer-related serum tumor markers, CT scan and dynamic+static 18F-FDG PET/CT features of a patient diagnosed with NUTM1-rearranged sarcoma by pathological and genetic test results to deepen the understanding of the imaging features of this disease." (PMID 41001035, 2025). "Herein, we present a case of a 26-year-old man with an NSD3::NUTM1 fusion sarcoma." (PMID 39200173, 2024). "Thus, the pathological diagnosis was NUTM1 rearrangement sarcoma." (PMID 41001035, 2025). "Therefore, a sarcoma with NUTM1 rearrangement was considered." (PMID 41001035, 2025). "Additionally, it indicates that the NSD3::NUTM1 fusion can drive sarcoma genesis." (PMID 39200173, 2024). "There are several partner genes related to the CIC gene in CIC rearranged sarcoma, including DUX4, FOXO4, LEUTX, NUTM1, and NUTM2A, with the most common fusion type being CIC-DUX4." (PMID 40255429, 2025). "Functional studies to elucidate the molecular pathogenesis of CIC::NUTM1 and CIC::FOXO4 sarcomas and identify therapeutic targets are warranted." (PMID 38882060, 2024). "“CIC fused sarcoma” group consisted of CIC::DUX4 (n = 22), CIC break (FISH) (n = 7) and ATXN1::NUTM1 (n = 2)." (PMID 37212486, 2023). "All CIC‐rearranged sarcomas have a fusion of CIC transcriptional repressor with various partners, most often DUX4, but also NUTM1 or NUTM2 have been observed." (PMID 35266242, 2022). "While in most peripheral CIC‐rearranged sarcomas the fusion partner is DUX4, in the brain the most common fusion partner is NUTM1." (PMID 35266242, 2022). "Sarcoma patients harboring the CIC::FOXO4 fusion also had a high rate of pulmonary metastasis (75%; total n = 4), while patients with the CIC::NUTM1 tumors had the lowest overall rate of metastasis (25%; total n = 12) with distant sites including the lungs, thyroid, bone, and brain." (PMID 38882060, 2024). "Moreover, CIC fusion to non-DUX4 genes such as FOXO4, NUTM1, and NUTM2A seems to lead to histology and features similar to those with CIC-DUX4, although CIC-LEUTX sarcomas are related to CD31 and ETS-related gene expression." (PMID 31676869, 2019).
sarcoma (continued). "Notably, we did not detect any immunoexpression of NUTM1 using the monoclonal antibody in contrast to the reported weak multifocal cross‐reactivity in MAD::NUTM2 fusion sarcomas." (PMID 40944358, 2025). "Possibly, sarcomas that appear compatible with a diagnosis of MPNST but show NUT fusions could be analogous to CIC::NUTM1 fusion tumors, in which the CIC fusion protein drives the phenotypic and methylation profile of the cancer to align with classic CIC-fused sarcomas." (PMID 39200173, 2024). "The NSD3::NUTM1 fusion has not been previously reported in a sarcoma." (PMID 39200173, 2024). "Additionally, tumors involving ATXN1 rearrangements—such as ATXN1::NUTM1 and ATXN1::NUTM2—may cluster with CIC-rearranged sarcomas by methylation profiling, despite lacking a CIC gene fusion." (PMID 40722508, 2025).
Poroma (12 papers, 2019 to 2025). A benign adnexal neoplasm composed of EPITHELIAL CELLS. "Rearrangement in NUTM1 has been associated with poorly differentiated carcinomas with variable squamous differentiation originating in midline organs as well as in various other neoplasms including sarcoma-like tumors, poromas, and acute lymphoblastic leukemias." (PMID 35501919, 2022). "Furthermore, detection of NUTM1 rearrangements in benign poromas as well precludes the notion that the NUTM1 gene is a lethal fusion partner in neoplasms and underlines the evolving and continuous role of standard histology and phenotyping in diagnosis and classification of neoplasms." (PMID 32436169, 2020). "Both poromas and porocarcinomas harbor activating mutations in HRAS, or fusions of YAP/TAZ, YAP1-MAML2, YAP1-NUTM1, or WWTR1_NUTM1." (PMID 37627947, 2023). "Poroma is a benign skin adnexal tumor, a subset of which harbor NUTM1-rearrangements and resection is curative." (PMID 34898574, 2021). "Furthermore, the immunohistochemistry of testicular nuclear protein (NUT) can screen for NUTM1 translocations in PC and poroma." (PMID 36358649, 2022). "Recent sequencing of these tumors demonstrated that 90% of poromas and ~70% of porocarcinomas exhibit YAP1 or WWTR1 gene fusions, with YAP1 fused to either MAML2 or NUTM1 and WWTR1 fused to NUTM1." (PMID 40491864, 2024). "Most poromas and porocarcinomas harbor YAP1::MAML2/NUTM1 or, rarely, WWTR1::NUTM1 fusions." (PMID 41350449, 2025).
germ cell tumor (7 papers, 2015 to 2025). A benign or malignant, gonadal or extragonadal neoplasm that originates from germ cells. "Native NUTM1 protein expression is localized to the nucleus and it has been identified in germ cells of the testis and ovary, ciliary body, germ cell tumors (where protein expression is weak), and NUTM1-rearranged tumors." (PMID 35372003, 2022). "Under normal circumstances, the expression of wild-type NUTM1 is restricted to the testes and any expression outside the testes (or a germ cell tumor) can be interpreted as the pathologic expression of an NUTM1 fusion gene driven by the promoter of its fusion partner." (PMID 35957893, 2022). "However, one should be cautious in interpreting the NUT immunostain because germ cell tumors can be focally NUT positive without NUTM1 gene rearrangement and rare cases are NUTM1-fusion positive with negative or only focal positive NUT immunostain." (PMID 34898574, 2021).
leukemia (7 papers, 2016 to 2024). A malignant (clonal) hematologic disorder, involving hematopoietic stem cells and characterized by the presence of primitive or atypical myeloid or lymphoid cells in the bone marrow and the blood. "We compared these to four other leukemias: NUTM1-rearranged infant B-ALL (n = 1), KMT2A-rearranged infant AML (n = 1), megakaryoblastic neonatal AML (n = 1) and childhood ETV6-RUNX1 B-ALL (a common subtype of standard-risk childhood B-ALL; n = 1)." (PMID 35288693, 2022). "The NUTM1 gene was expressed in the testis only and was absent in the CC, BC, and leukemia tissues." (PMID 35627192, 2022).
lung carcinoma (6 papers, 2015 to 2023). "Thus, although we cannot exclude misclassification of SBC-3 cells, our preclinical data support evidence that functional NUTM1 fusions are present in tumours diagnosed as lung cancer, and could represent an actionable driver event in these tumours with immediate potential clinical implications." (PMID 31097696, 2019).
thyroid carcinoma (4 papers, 2022 to 2024). "In summary, we present an NSD3::NUTM1 fusion thyroid carcinoma clearly showing thyrocyte differentiation, including colloid production and poorly formed follicles." (PMID 34997561, 2022). "In this report, we present a high-grade thyroid carcinoma with an NSD3::NUTM1 fusion detected on expanded next-generation sequencing testing." (PMID 34997561, 2022). "Identification of this histologically unusual tumor as a NUTM1 fusion thyroid carcinoma required recognition of the histology as unusual, perfoming a panel of IHC antibody stains, and following up initial negative genetic test results with extended molecular genetic testing." (PMID 34997561, 2022). "This exceptional case suggests that NUTM1 fusions may occur in an unknown number of aggressive thyroid carcinomas, possibly with distinctive histologic features but with thyrocyte differentiation." (PMID 34997561, 2022). "Thus, at the molecular genetic level, three of the now four reported cases of primary thyroid carcinomas with NUTM1 fusions, including our case, contained the NSD3 fusion partner." (PMID 34997561, 2022). "Moreover, thyroid carcinomas with NUTM1 fusions may be amenable to treatment with NUT carcinoma-targeted therapy such as a bromodomain and extraterminal domain protein small molecular inhibitor (BETi)." (PMID 34997561, 2022). "This case is the first reported of a thyroid carcinoma exhibiting thyrocyte differentiation and an NSD3::NUTM1 fusion." (PMID 34997561, 2022). "In a case of a thyroid carcinoma with unusual morphology and absence of BRAFV600E and RAS mutations (assessed by IHC or targeted genetic testing), a broader NGS panel that includes capacity to detect NUTM1 fusions may be considered in the workup of the tumor." (PMID 34997561, 2022).
acute lymphoblastic leukemia (3 papers, 2021 to 2022). Leukemia with an acute onset, characterized by the presence of lymphoblasts in the bone marrow and the peripheral blood. "Up to 5% of infant acute lymphoblastic leukemia harbors NUTM1-rearrangement and appears to have a better prognosis." (PMID 34898574, 2021). "NUTM1-rearranged B-ALL was associated with BMI1 (a proto-oncogene, which enhances the self-renewal of hematopoietic stem cells and can convert BCR-ABL1-positive progenitor cells to acute lymphoblastic leukemia) upregulation." (PMID 34898574, 2021). "Up to 21.7% of KMT2A-wildtype B-ALL in infants enrolled in interfant studies (a large international consortium on infant acute lymphoblastic leukemia) harbored NUTM1-rearrangement." (PMID 34898574, 2021).
skin adnexal neoplasm (3 papers, 2020 to 2024). "Notably, our diagnosis before and after detection of the NUTM1 gene fusion was concordantly that of an unusual type of malignant skin adnexal neoplasm (adnexal carcinoma) of the auditory canal." (PMID 32436169, 2020).
acute myeloid leukemia (2 papers, 2020 to 2025). Acute myeloid leukemia (AML) is a group of neoplasms arising from precursor cells committed to the myeloid cell-line differentiation. "Gene fusions involving NUTM1 have been increasingly recognized in hematologic malignancies, though their role in acute myeloid leukemia (AML) remains poorly understood." (PMID 41373823, 2025).
embryonal tumor (2 papers, 2022 to 2024). "A case report showed that a novel fusion gene of PARD3B and NUT midline carcinoma family member 1 (NUTM1) was discovered in an aggressive primary central nerve system (CNS) embryonal tumor." (PMID 36013056, 2022).
eosinophilia (2 papers, 2021 to 2024). "Some extremely rare fusion genes, such as CSNK2A1::PDGFRB, CBFB::MYH11, and NSD3::NUTM1, have been identified in patients with eosinophilia using RNA−seq techniques." (PMID 38992589, 2024).
glioblastoma (2 papers, 2024 to 2025). The most malignant astrocytic tumor (WHO grade IV). "Additionally, NUTM1 subtype showed subtype-specific expression of ZNF311, which is potentially a novel biomarker for assessing prognosis and immune infiltration in glioblastoma." (PMID 41246237, 2025).
ovarian carcinoma (2 papers, 2022 to 2024). A malignant neoplasm originating from the surface ovarian epithelium. "Similarly, the role of NUTM1 in patients with ovarian cancer is unclear." (PMID 35501919, 2022).
acute leukemia (1 paper, 2024). A clonal (malignant) hematopoietic disorder with an acute onset, affecting the bone marrow and the peripheral blood. "We also assessed gene sets derived from more differentiated acute leukemias, including granulocyte–monocyte progenitor-like AML21, myeloid-like AML24, NUTM1-rearranged ALL19, and signatures for BCR-ABL + B-ALL spanning later B-cell differentiation." (PMID 39294124, 2024).
adenocarcinoma of the appendix at (1 paper, 2025). "Patients EOCRC#23 (adenocarcinoma of the appendix at 36 years of age) and EOCRC#51 (colon cancer diagnosed at 38), from unrelated families, carried the same TV in NUTM1." (PMID 40429818, 2025).
B-cell lymphomas (1 paper, 2021). "Two large gene expression data sets were probed for the expression of IGF2BP3—the highest levels were seen among the B-cell lymphomas of a germinal center origin and well-established (KMT2A-rearranged and ETV6-RUNX1) and novel subtypes of B-ALL (e.g., NUTM1 and ETV6-RUNX1-like)." (PMID 33805930, 2021).
lung sarcoma (1 paper, 2025). A malignant mesenchymal neoplasm that arises from the lung. "In the future, further attention will be paid to the mining of imaging features of NUTM1-rearranged lung sarcoma and the value of each metabolic parameter in differential diagnosis, staging, efficacy assessment and prognostic evaluation." (PMID 41001035, 2025). "This case demonstrates the features of NUTM1-rearranged lung sarcomas on 18F-FDG PET/CT and highlights the value of this imaging technique in the differential diagnosis and staging of malignant tumours." (PMID 41001035, 2025). "This case demonstrates the characteristics of NUTM1-rearranged lung sarcomas on 18F-FDG PET/CT and highlights the value of this imaging technique in the differential diagnosis and staging of malignant tumours." (PMID 41001035, 2025). "Most reports are dominated by case reports of the pathological features of NUTM1-rearranged lung sarcoma have been under-recognised." (PMID 41001035, 2025). "This study aimed to identify the static and dynamic features of 18F-FDG PET/CT in NUTM1-rearranged lung sarcomas." (PMID 41001035, 2025). "The value of static and dynamic metabolic parameters in the differential diagnosis, staging, efficacy and prognostic assessment of NUTM1-rearranged lung sarcoma needs to be explored by collecting more cases." (PMID 41001035, 2025). "This case shows dynamic and static 18F-FDG PET/CT and pathological features of NUTM1-rearranged lung sarcomas." (PMID 41001035, 2025). "NUTM1-rearranged lung sarcomas can occur at any age and are gender-neutral, with an atypical clinical presentation, aggressive nature and poor prognosis." (PMID 41001035, 2025). "Nuclear protein of testis midline carcinoma family member 1 (NUTM1)-rearranged lung sarcomas are rare malignant malignancies." (PMID 41001035, 2025). "Final pathological and genetic test results confirmed NUTM1-rearranged lung sarcoma." (PMID 41001035, 2025). "Final pathology and genetic testing confirmed NUTM1-rearranged lung sarcoma." (PMID 41001035, 2025). "In this case, we describe the clinical, CT, dynamic and static 18F-FDG PET/CT scan features of a patient diagnosed with NUTM1-rearranged lung sarcoma, as confirmed by pathological and genetic test results, to further our understanding of the imaging features of this disease." (PMID 41001035, 2025). "Currently, there are very few reports on NUTM1-rearranged lung sarcomas." (PMID 41001035, 2025). "The imaging features of NUTM1-rearranged lung sarcoma have been under-recognised." (PMID 41001035, 2025). "As NUTM1-rearranged lung sarcoma is so rare, there are currently no relevant studies on imaging-based differential diagnosis." (PMID 41001035, 2025).
malignant peripheral nerve sheath tumor (1 paper, 2024). Malignant peripheral nerve sheath tumor (MPNST) is a rare and often aggressive soft tissue sarcoma occurring in a wide range of anatomical sites. "Here, we present a case of a 26-year-old man with a history of a multiply recurrent malignant peripheral nerve sheath tumor (MPNST) whose tumor was found to harbor an oncogenic NSD3::NUTM1 fusion." (PMID 39200173, 2024).
myelodysplastic syndrome (1 paper, 2023). A clonal hematopoietic disorder characterized by dysplasia and ineffective hematopoiesis in one or more of the hematopoietic cell lines. "Furthermore, genetic fusions of NSD3 with NUP98 and NUTM1 genes have been described in patients with AML as well as myelodysplastic syndrome, and primary pulmonary NUT carcinoma, respectively." (PMID 37062069, 2023).
soft tissue sarcoma (1 paper, 2023). A malignant neoplasm arising from muscle tissue, adipose tissue, blood vessels, fibrous tissue, or other supportive tissues excluding the bones. "These new “CIC fused” (CIC‐fused/ATXN1::NUTM1) and “BCOR rearranged” (BCOR fused/ITD/ YWHAE) soft tissue sarcomas (STS) are not well described." (PMID 37212486, 2023).
soft tissue tumors (1 paper, 2024). "Beyond the epithelial tissue, a few cases of soft tissue tumors have been reported to carry BRD3/4::NUTM1 fusion genes, suggesting that the fusion gene can also collaborate with mesoderm-derived mesenchymal gene regulatory networks (GRNs) to drive NC." (PMID 38724194, 2024).